SNAP25 (synaptosome associated protein 25)
Diseases named in the same sentence as SNAP25 in open-access papers (continued):
Sharing a sentence is not in itself a finding about the gene and the disease.
Cognitive impairment (43 papers, 2013 to 2026). Abnormal cognition is characterized by deficits in thinking, reasoning, or remembering. "Patients carrying SNAP25 mutations frequently present with neurodevelopmental disorders, including intellectual impairment, motor retardation, and epilepsy, as reported in prior studies." (PMID 41401185, 2025). "Single-nucleotide polymorphisms of the SNAP25 gene are associated with cognitive test performance in healthy individuals and subjects with AD and mild cognitive impairment." (PMID 38528511, 2024). "Snap25 deficiency has been implicated in a variety of cognitive disorders, and it was significantly decreased early post 30 Gy." (PMID 38891920, 2024). "It is suggested that chronic reductions in SNAP25 levels are associated with intellectual impairment, psychiatric disorders, and ADD." (PMID 38542104, 2024). "In this study, we investigated the role and underlying mechanism of SNAP‐25 MnlI variant in cognitive impairment and brain functions in boys with ADHD." (PMID 36068994, 2022). "Previous studies from patients with AD have suggested that synaptophysin is more vulnerable than other synaptic proteins such as syntaxin or SNAP-25, and loss of synaptophysin is an early event that correlates with initial cognitive impairment." (PMID 35855335, 2022). "SNAP‐25 hypo‐activity and hyper‐activity are implicated in various cognitive disorders, such as ADHD." (PMID 36068994, 2022). "Nevertheless, SNAP-25 is known to play a role in cognitive functions and regulation of locomotor activity, and consequently, associations of this protein with cognitive disorders and hyperactivity have been demonstrated." (PMID 32367505, 2020). "The evidence demonstrated that miR-210-5p mediates the cognitive impairment effects of chronic cerebral ischemia-induced VD by suppressing the expression of Snap25, which leads to synaptic loss." (PMID 30483048, 2018). "miR-210-5p also likely targets other mRNAs, but miR-210-5p–Snap25-postsynapse pathway is sufficient to explain the role of miR-210-5p regulation of synaptic loss and cognitive impairment in early VD." (PMID 30483048, 2018). "Also, studies revealed SNAP25 delivers significant association of the neurogranin and cognitive impairment from PD patients." (PMID 41327336, 2025). "However, thus far, the underlying mechanism of SNAP‐25 in these cognitive disorders has been poorly characterized." (PMID 36068994, 2022). "Furthermore, the genetic variants in SNAP25 have been found associated with cognitive ability and cognitive disorder." (PMID 30083479, 2018). "In particular, in ASD children SNAP-25 polymorphisms were shown to be associated with hyperactivity and cognitive impairment, leading to the hypothesis that the functioning of synapses related with cognitive activity are influenced by different expression of SNAP-25 protein." (PMID 36649268, 2023). "Decreased levels of SNAP25 expression have been described in disease states characterized by increased network excitability and possibly associated with neurotoxicity and in elderly individuals with Alzheimer’s and Down syndrome who also Alzheimer’s like pathology and cognitive impairment." (PMID 24600537, 2013). "In AD patients with mild cognitive impairment, SNAP25 was elevated in cerebrospinal fluid and had a strong association with t-tau." (PMID 38053192, 2023). "The reduction or loss of SNAP-25, SY1A, SYT1, and SYN expressions causes memory impairment and cognitive deficit in AD." (PMID 36873105, 2023). "Our previous research demonstrated that SNAP25 mitigated surgery-induced cognitive impairment by enhancing PTEN-induced kinase 1 (PINK1)/Parkin-dependent mitophagy as well as repressing caspase-3/gasdermin E (GSDME)-dependent pyroptosis." (PMID 38102610, 2023). "The reduction of SNAP25 mRNA expression suggests that presynaptic dysfunction contributes to cognitive deficits in neurodegeneration." (PMID 36129947, 2022).
Cognitive impairment (continued). "A recent study has demonstrated that SNAP25 is an effective biomarker for predicting AD 5–7 years before cognitive impairment." (PMID 34194312, 2021). "Mild to severe cognitive impairment has been reported in patients carrying mutations in the SLC5A7 gene, DPAGT1 gene, SNAP25 gene, COL13A1 gene, MYO9A gene, MUNC13–1 gene, and in SCN4A-related CMS." (PMID 30808424, 2019). "In the current study, Snap25 was directly downregulated by miR-210-5p in vitro and in vivo, which confirms that overexpression of miR-210-5p leads to cognitive defects." (PMID 30483048, 2018). "Altogether, miR-210-5p contributes to cognitive impairment in chronic ischemia-induced VD model through the regulation of Snap25 expression, which potentially provides an opportunity to develop a new therapeutic strategy for VD." (PMID 30483048, 2018). "In summary, our data demonstrate that miR-210-5p contributes to cognitive impairment in early VD in rats though targeting Snap25." (PMID 30483048, 2018). "Our findings are consistent with prior studies showing higher SNAP-25, synaptotagmin-1, GAP-43, and neurogranin levels in CSF are associated with cognitive impairment in AD, which may be linked to synapse degeneration in the brain." (PMID 38299587, 2024). "One previous study showed that SNAP-25 was elevated in the CSF of patients with mild cognitive impairment (MCI) and AD, indicating that SNAP-25 may be a useful biomarker reflecting synapse degeneration." (PMID 30524269, 2018). "Thus, NT-5/CD63 in serum EVs might be useful for the diagnosis of mild cognitive impairment, as in the case of SNAP25." (PMID 38321007, 2024). "A recent Chinese study revealed that exosomal SNAP25, GAP43, neurogranin, and synaptotagmin-1, combined with APOE ε4 status, improved diagnostic accuracy (AUC = 0.88), acting as a useful biomarkers panel for the prediction of AD five to seven years before cognitive impairment." (PMID 35360215, 2022). "We found that SNAP-25 and NFL were increased in mild cognitive impairment and Alzheimer’s disease compared with the subjective cognitive decline group and as well as in patients with β-amyloid pathology." (PMID 37680670, 2023). "Taken together, these findings support the idea that TNFAIP1 silencing mitigates postoperative cognitive impairment, intensifies PINK1/Parkin-mediated mitophagy and restrains caspase-3/GSDME-mediated pyroptosis by stimulating SNAP25 protein expression." (PMID 38102610, 2023). "This reduction of SNAP-25, SY1A, SYT1, and SYN leads to cognitive impairment and memory dysfunction, which can be reversed by an increase in SNAP-25, SY1A, SYT1, and SYN following the blockage of presynaptic N-type VGCCs with omega-agatoxin-Aa2a." (PMID 36873105, 2023). "To investigate whether increases in Gap43 and Snap25 could alleviate the cognitive impairment of 5×FAD, we designed an EV-based system to overexpress Gap43 and Snap25 in the neural cells of the 5×FAD mouse brain." (PMID 38528511, 2024). "Recently, the mechanism of cognitive impairment has been shown to be related to decreases in SYP, PSD-95, and SNAP-25 levels, which may alter the presynaptic integrity triggered by the loss of dopaminergic degeneration." (PMID 37568205, 2023). "SNAP-25, however, is less studied in patients with cognitive impairment without Aβ pathology, e.g., FTD, PSP, and CBD." (PMID 35659284, 2022). "Expression of VAMP2, Syntaxin1, and SNAP-25 is reduced in human AD brain samples, and intracellular Aβ oligomers have been shown to bind to SNARE proteins and thereby inhibit the SNARE complex formation, blocking neurotransmission and exacerbating cognitive defects." (PMID 39773760, 2025). "Moreover, we found significantly lower CSF SNAP-25 (p = 0.025), β-synuclein (p = 0.044), and neurogranin (p = 0.007) levels in PwMS with vs. without domain-specific cognitive impairment." (PMID 39708160, 2024).
Alzheimer disease (36 papers, 2013 to 2025). A progressive, neurodegenerative disease characterized by loss of function and death of nerve cells in several areas of the brain leading to loss of cognitive function such as memory and language. "The presynaptic protein, synaptosomal‐associated protein 25 kDA (SNAP‐25), is crucial for synaptic transmission and has been suggested as a biomarker in Alzheimer's disease (AD)." (PMID 39912369, 2025). "Previous studies found that the genetic polymorphism of SNAP-25 was correlated with Alzheimer’s disease (AD) and Parkinson’s disease (PD) progression." (PMID 39551143, 2024). "The SNAP-25 rs363050 (AA) polymorphism was significantly more frequent in sarcopenic patients; interestingly this SNAP-25 polymorphism was shown to associate with other age-dependent pathologies, including Alzheimer’s disease and Type 2 Diabetes mellitus." (PMID 34289870, 2021). "For example, both SNAP-25 SNPs rs363,043 and rs363,050 are associated with Alzheimer’s disease, and SNAP-25 expression levels are decreased in multiple regions of the brains of Alzheimer’s patients." (PMID 34638726, 2021). "Misregulation of SNAP-25 is associated with several human diseases and neurodegenerative disorders including Huntington’s Disease, Alzheimer’s Disease, and diabetes." (PMID 23451149, 2013). "In post-mortem studies of the tauopathy Alzheimer’s disease, there is a biphasic synaptic protein response during disease progression, with increases in synaptophysin/syntaxin/SNAP-25 in early Braak stages and synaptic loss observed only when the disease has progressed to the neocortex." (PMID 34398211, 2022). "Snap25 plays an important role in exocytosis, and its polymorphisms have been implicated in modulating the release of neurotransmitters in a number of neurologic conditions including autism and Alzheimer's disease (AD)." (PMID 26779543, 2016). "GSEA of SNAP25 revealed that Alzheimer’s disease, cytokine–cytokine receptor interaction, and notch signaling pathway were identified, showing an overall upregulation trend." (PMID 41009659, 2025). "This selection was made to scrutinize the influence of the APOE genotype on the modulation of the VAMP2/SYNTAXIN1/SNAP25 protein complex system within the brains of individuals with Alzheimer’s disease." (PMID 40003632, 2025). "As a result, the majority of these markers (CSF Ng, VILIP-1, sTREM2, SNAP-25) are likely to provide minimal utility in the context of Alzheimer’s disease." (PMID 38505230, 2024). "Postmortem studies of Alzheimer’s disease brains have shown altered levels of several synaptic proteins, including SNAP25 and synaptogamins, components of the SNARE complex." (PMID 37429912, 2023). "Previous studies suggested SNAP25 as a biomarker in Alzheimer’s disease (AD), with reduced levels in AD26, as well as for Creutzfeldt-Jacob Disease patients." (PMID 37491426, 2023). "Of note, an altered SNARE complex has been also observed in Parkinson's (PD) and Alzheimer's disease (AD), where the cerebrospinal fluid levels of SNAP25 have been suggested to be representative of the progressive loss of synapse preceding neuronal loss." (PMID 37488208, 2023). "We focused here on presynaptic mGlu2/3 because of their exquisite localisation in Alzheimer’s disease-relevant brain areas and their established role in sequestering synaptic SNAP25." (PMID 36116796, 2022). "In another study, there were significantly higher levels of serum SNAP-25 in patients with atypical Alzheimer’s disease compared with controls." (PMID 33578866, 2021). "In another study, mean values of SNAP-25, syntaxin, and synaptophysin levels were significantly reduced by 21–28% in the prefrontal cortex of Alzheimer’s disease patients compared with controls." (PMID 33578866, 2021). "There were decreases in synaptophysin and synaptobrevin levels by approximately 30% and 10% in levels of SNAP-25 and synaptotagmin in the brain of Alzheimer’s disease patients compared with controls." (PMID 33578866, 2021).
Alzheimer disease (continued). "Snap25 was found to be an important gene involved in metabolic and neural diseases such as obesity, diabetes, and Alzheimer’s disease." (PMID 33525381, 2021). "Noticeably, CSF SNAP-25 levels reduced longitudinally in the group of Alzheimer’s disease patients followed for 4 years." (PMID 33578866, 2021). "Studies have assessed the levels of synaptic proteins such as SNAP-25, β, syntaxin, and synaptotagmin in the brains of Alzheimer’s disease patients and in controls." (PMID 33578866, 2021). "We found that the levels of SNAP-25 were significantly lower in the Alzheimer’s disease group for the membrane-bound and the membrane-raft associated fractions." (PMID 25418885, 2014). "Our results show that SNAP-25 is a promising novel CSF biomarker for synapse degeneration in Alzheimer’s disease." (PMID 25418885, 2014). "The CSF levels of two of the tryptic peptides of SNAP-25 (Ac-2-16 and 17-31) were significantly higher in patients with Alzheimer’s disease compared with controls in two of the three examined clinical cohorts." (PMID 25418885, 2014). "We found significantly higher levels of SNAP-25 in CSF in Alzheimer’s disease in three separate cohorts, including in the very early stage of the disease." (PMID 25418885, 2014). "We found significantly higher levels of cerebrospinal fluid SNAP-25 fragments in Alzheimer’s disease, even in the very early stages, in three separate cohorts." (PMID 25418885, 2014). "We demonstrate significantly higher levels of SNAP-25 in CSF samples from patients with prodromal Alzheimer’s disease and Alzheimer’s disease compared with controls." (PMID 25418885, 2014). "By applying this novel affinity mass spectrometry strategy on three separate cohorts of patients, the value of SNAP-25 as a cerebrospinal fluid biomarker for synaptic integrity in Alzheimer’s disease was assessed for the first time." (PMID 25418885, 2014). "In conclusion, the present study delved into the effects of APOE4 on the VAMP2/SYNTAXIN1/SNAP25 complex through molecular dynamics simulations, revealing the mechanism by which it may contribute to early synaptic dysfunction in Alzheimer’s disease (AD)." (PMID 40003632, 2025). "Importantly, the selective inhibition of tau release by cleavage of SNAP25 by BoNT/A was confirmed also in human Alzheimer’s disease brain synaptosomes." (PMID 36116796, 2022). "Besides its crucial role in developmental disorders, SNAP-25 is involved in aging-related disorders such as Alzheimer’s disease." (PMID 34638726, 2021). "Furthermore, neurogranin and other synaptic biomarkers such as Rab3 and SNAP25 were found to predict cognitive decline in patients with Alzheimer’s disease and dementia of Lewy bodies." (PMID 33578866, 2021). "Serum exosome SNAP-25 is a potential biomarker of Alzheimer’s disease." (PMID 32848539, 2020). "The tryptic peptide assays of SNAP-25 (32-40, 17-31, and Ac-2-16) could each differentiate Alzheimer’s disease from controls." (PMID 25418885, 2014). "Two of the SNAP-25 peptides (17-31 and 32-40) could also be used to differentiate prodromal Alzheimer’s disease and overt Alzheimer’s disease." (PMID 25418885, 2014). "Moreover, two of the SNAP-25 peptides (amino acids 17-31 and 32-40) were significantly higher in Alzheimer’s disease compared with prodromal Alzheimer’s disease." (PMID 25418885, 2014). "Previous studies show that synaptosomal-associated protein 25 (SNAP-25) and synapsin 2 (SYN2) genes associated with synaptic vesicle release, were among the most prominently downregulated differentially expressed genes in the prefrontal cortex of humans with Alzheimer’s disease (AD)." (PMID 36293516, 2022). "Moreover, CSF SNAP-25 levels, determined using mass spectrometry, were significantly elevated in early-stage and established Alzheimer’s disease, and the biomarker was able to meaningfully discriminate patients with the disease from healthy controls with an area under the curve of 0.901." (PMID 33578866, 2021).
Alzheimer disease (continued). "In the present study, CSF SNAP-25 peptides were already increased in prodromal Alzheimer’s disease compared with controls, supporting the notion that this synaptic marker might provide an early marker for Alzheimer’s disease." (PMID 25418885, 2014). "This is the first study demonstrating that SNAP-25 might be a useful CSF biomarker in differential diagnosis of patients with Alzheimer’s disease/prodromal Alzheimer’s disease from controls and also in discriminating Alzheimer’s disease from prodromal Alzheimer’s disease." (PMID 25418885, 2014). "Four hub genes, GFAP, NPY, SNAP25, and SST, were found as possibly hub aging-related genes in Alzheimer’s disease from machine algorithms by adopting the random forest, LASSO, SVM, and Boruta models." (PMID 41009659, 2025). "Through co-expression modular analysis, we identified that the genes diminished in Alzheimer’s disease are most enriched in module 1 (M1) that contains SNARE-binding complex genes, including the core SNARE genes, SNAP-25, STX1A and VAMP2." (PMID 34423299, 2021). "Many of the SNARE complex genes involved in presynaptic vesicle exocytosis were significantly downregulated in Alzheimer’s disease, including SNAP-25, STX1A, SYT1 and VAMP2, while STX2, SYN1 and VAMP3 were not changed." (PMID 34423299, 2021). "We used flow cytometry to analyze microvesicles carrying tau, phospho-tau-Thr181, phospho-tau-Ser202Thr205, synaptophysin, and SNAP-25 in the cerebrospinal fluid of 19 patients with Alzheimer’s disease and 15 non-inflammatory neurological disease controls." (PMID 34295239, 2021). "Previous studies have shown that the expression level of SNAP25 in exosomes and cerebrospinal fluid of Alzheimer’s disease patients were significantly down-regulated compared with normal counterparts." (PMID 34497527, 2021). "The tryptic peptides of SNAP-25 (Ac-2-16 and 17-31) correlated with Aβ1-42 in the control group, but not in patients with Alzheimer’s disease." (PMID 25418885, 2014). "The CSF levels of all three investigated tryptic peptides of SNAP-25 were significantly higher in patients with prodromal Alzheimer’s disease and overt Alzheimer’s disease compared with non-demented controls." (PMID 25418885, 2014). "There were no cohort effects on the CSF levels of novel SNAP-25 biomarkers, P-tau181 or Aβ1-42 (data not shown), allowing statistical analyses of the entire group of participant samples from Alzheimer’s disease (N = 36) and controls (N = 32)." (PMID 25418885, 2014). "Consistently, the CSF levels of all tryptic peptides of SNAP-25 were significantly higher in patients with Alzheimer’s disease compared with non-demented controls in the replication set." (PMID 25418885, 2014). "They revealed that the presynaptic (synaptosomal-associated protein 25 (SNAP25), growth associated protein 43 (GAP43)) and postsynaptic markers (Ng) are elevated in CSF in early Alzheimer’s disease, i.e., in Aβ-positive individuals without evidence of tau pathology." (PMID 39769345, 2024).